IGF1R (insulin like growth factor 1 receptor)
Diseases named in the same sentence as IGF1R in open-access papers (continued):
Sharing a sentence is not in itself a finding about the gene and the disease.
embryonal tumors (1 paper, 2012). "Together, our studies demonstrate the potential of targeting the IGF-1R/PI3K signaling axis in embryonal tumors." (PMID 23056595, 2012). "Indeed the first results from clinical trials evaluating the safety and efficacy of IGF-1R neutralizing antibodies in children and adolescents with embryonal tumors have been reported." (PMID 23056595, 2012).
emphysema (1 paper, 2024). "AT2-specific overexpression of IGF2 and IGF-1R/IR signaling activation was also observed in emphysema and tumor lesions of the lungs in patients with a history of TS." (PMID 38902841, 2024).
endometrial tumors (1 paper, 2019). "Furthermore, the IGF1R emerged in recent years as a promising therapeutic target in oncology, including endometrial tumors." (PMID 31320996, 2019).
endometritis (1 paper, 2025). An acute or chronic, usually bacterial infectious process affecting the endometrium. "In cows with endometritis, let-7d expression was increased while IGF1R expression was decreased, suggesting an inverse relationship." (PMID 40298790, 2025).
epithelial ovarian tumors (1 paper, 2011). "In malignant epithelial ovarian tumors, the positive rate of IGF-1R detection (93.33%) was significantly higher than those in marginal (63.33%) (P < 0.05), benign (53.33%) (P < 0.05), and normal ovarian samples (40%) (P < 0.01)." (PMID 22072919, 2011).
estrogen resistance (1 paper, 2021). "Anti-estrogen resistance in ER-positive breast cancer is associated with activated insulin-like growth factor 1 receptor (IGF1R)." (PMID 33462336, 2021).
familial cancer (1 paper, 2017). "Loss-of-function mutation of BRCA1 in familial cancer may abolish its inhibitory role, leading to constitutive hyperactivation of the IGF1R gene, a typical hallmark of cancer cells." (PMID 28706506, 2017).
Fanconi anemia (1 paper, 2019). Fanconi anemia (FA) is a hereditary DNA repair disorder characterized by progressive pancytopenia with bone marrow failure, variable congenital malformations and predisposition to develop hematological or solid tumors. "qRT-PCR data confirmed that the expression of Fanconi anemia-associated genes including BRCA1, BRCA2, PALB2, and RAD51 and cancer-associated genes (ALDH1A3 and IGF1R) was strongly inhibited by FR treatment, as shown by microarray analysis." (PMID 30719229, 2019).
female infertility (1 paper, 2025). Diminished or absent ability of a female to achieve conception. "The let-7 family upregulation in ovarian endometriosis disrupts GC metabolism and redox balance through IGF1R inhibition, which supports the role of redox-sensitive miRNAs in female infertility." (PMID 41283253, 2025).
GNE myopathy (1 paper, 2022). "In a HEK cell–based model of GNE myopathy, mitochondria-dependent apoptosis and IGF-1R phosphorylation were observed, and IGF-1R hyposialylation led to AKT phosphorylation and downregulation of the ERK pathway, which may rescue apoptotic cell death of GNE-deficient cell lines through Bcl-2." (PMID 35904705, 2022).
Gynecomastia (1 paper, 2025). Abnormal development of large mammary glands in males resulting in breast enlargement. "The study highlighted CT-707 as a small molecule inhibitor of IGF1R for the first time and also suggested that CT-707 may be a potential treatment for gynecomastia." (PMID 40002676, 2025). "Our findings highlight the potential therapeutic relevance of targeting pathways involved in growth factor signaling (e.g., IGF1R and TGFB1), androgen receptor modulation and melanocortin signaling for managing gynecomastia." (PMID 40002676, 2025).
hematoma (1 paper, 2014). A hematoma is a collection of blood from a vascular structure into an extravascular space. "The neuroprotective effect of AM let7c is probably mediated by IGF1R up-regulation with decreased apoptotic cell death around the hematoma of 50% compared to controls." (PMID 24959881, 2014).
hemophilia (1 paper, 2014). Hemophilia is a genetic disorder characterized by spontaneous hemorrhage or prolonged bleeding due to factor VIII or IX deficiency. "Data presented suggest a primarily and predominantly disturbed biochemistry in OCD with differential regulation of IGF-1/IGF-1R, which is possibly more specific as the disturbed biochemistry in hemophilia, in which the whole inflammatory cascade is activated driven by the neutrophil influx." (PMID 24885831, 2014).
Hepatic failure (1 paper, 2013). "In hepatic stellate cells, KITLG expression stimulated by IGF1R signaling may facilitate the KIT-dependent recruitment of inflammatory cells in injury and fibrosis and progenitor cells in hepatic failure, and may thus be associated with both disease progression and tissue regeneration." (PMID 24116170, 2013).
hypogonadism (1 paper, 2023). A disorder characterized by decreased function of the gonads. "This could represent one of the mechanisms by which IGF1R or GHR defects are associated with delayed puberty or hypogonadism." (PMID 37685880, 2023).
idiopathic pulmonary arterial hypertension (1 paper, 2021). A sporadic form of pulmonary arterial hypertension (PAH) characterized by elevated pulmonary arterial resistance leading to right heart failure. "In addition, upregulation of insulin-like growth factor 1 receptor by degradation of miR-328-3p were observed in patients with idiopathic pulmonary arterial hypertension, which is a kind of cardiovascular disease." (PMID 34440082, 2021).
Impaired glucose tolerance (1 paper, 2019). An abnormal resistance to glucose, i.e., a reduction in the ability to maintain glucose levels in the blood stream within normal limits following oral or intravenous administration of glucose. "Although it should be necessary to measure IGF1R expression levels, IGF1R gene has been reported to be hypomethylated in placentas exposed to maternal impaired glucose tolerance, which suggests its potential implication in fetal programming." (PMID 30926763, 2019).
intrahepatic cholangiocarcinoma (1 paper, 2025). A carcinoma that arises from the intrahepatic bile duct epithelium in any site of the intrahepatic biliary tree. "IGF‐1 and IGF‐1R were expressed in all intrahepatic cholangiocarcinoma biopsies." (PMID 40304434, 2025).
ischemic cardiomyopathy (1 paper, 2009). Ischemic cardiomyopathy is a cardiomyopathy in which a weakness in the muscle of the heart due to inadequate oxygen delivery to the myocardium with coronary artery disease being the most common cause. "In this study, we show that the gene expressions of cyclins B, D1, D3 and E are increased in ischemic cardiomyopathy in relation to increased IGF-1 and IGF-1R expressions and echocardiographic measures of wall thickness but are not increased in tachycardiomyopathy." (PMID 19818143, 2009). "In the present study, there was an increased expression of IGF-1R in ischemic cardiomyopathy but not in tachycardiomyopathy, indirectly suggesting that parallel increased expressions of IGF-1 and its receptor are only to be observed in myocardial injury with a hypertrophic response." (PMID 19818143, 2009).
left ventricular hypertrophy (1 paper, 2013). Enlargement of the LEFT VENTRICLE of the heart. "Meta-analysis confirmed rs17132261 and rs2292462 were associated with left ventricular hypertrophy (p=1.03x10-8 and p=5.86x10-10 respectively) and one single nucleotide polymorphisms in IGF1R (rs4966014) became genome wide significant upon meta-analysis although was not significant in our study." (PMID 23879873, 2013).
lentivirus infection (1 paper, 2015). Virus diseases caused by the Lentivirus genus. "Immunoblotting analysis showed that the expression level of IGF1R in MDA-MB-231/IGF1R-KD and BT549/IGF1R-KD cells was reduced compared to EV control cells, suggesting that lentivirus infection was highly efficient at inhibiting IGF1R expression." (PMID 25749031, 2015).
leukoplakia (1 paper, 2017). A white patch or plaque on a mucous membrane that cannot be characterized clinically or pathologically as any other disease. "Notably, several sub-branches of ILK, IGF1R, HIF1, HGF, MAPK and WNT pathways were among the most differentially dysregulated axes between OSCC and leukoplakia, suggesting their role in the transition from non-invasive to invasive disease." (PMID 28580171, 2017).
lung NET (1 paper, 2020). "Our findings in the tumoral tissues, as well as the in vitro experiments with ZKK multi-kinase inhibitors, suggest that inhibition of IGF1R and MAPK15 could also be potentially effective in lung NET treatment." (PMID 33138224, 2020).
lung tumour (1 paper, 2016). "In the present study, we show a unique mechanism whereby the NNK-mediated Ca2+ signalling stimulates activation of the IGF-1R pathway, resulting in lung tumour development." (PMID 27666821, 2016). "We identified that increase in Ca2+ entry resulting from binding of NNK to nAChRs and activation of voltage-dependent Ca2+ channels (VDCCs) leads to exocytosis of IGF2 and activation of IGF-1R, ultimately promoting lung epithelial cell transformation and lung tumour formation." (PMID 27666821, 2016).
lymphedema (1 paper, 2025). Excess fluid collection in tissues, causing swelling. "Linsitinib restricted enlargement of small lymphatics and tissue swelling during lymphedema development, likely by inhibiting IGF1R-driven vascular endothelial growth factor-C (VEGF-C) synthesis by macrophages." (PMID 40060910, 2025). "The favorable safety profile of targeting IGF1R raises the possibility of using linsitinib or other IGF1R inhibitors, including IGF1R monoclonal antibodies, to treat secondary lymphedema in the clinic, potentially for long periods of time." (PMID 40060910, 2025). "Our findings suggest that linsitinib restricted pathological remodeling of initial and/or precollector lymphatics by blocking IGF1R-driven VEGF-C synthesis in the mouse lymphedema model." (PMID 40060910, 2025). "Overall, our findings indicate that further preclinical, and potentially clinical, development of IGF1R inhibitors for the treatment of secondary lymphedema is warranted." (PMID 40060910, 2025). "The molecular mechanisms by which IGF1R promoted recruitment of macrophages in our lymphedema model are unclear; however, a likely scenario is that the initial lymph stasis after surgery in our model promotes recruitment of macrophages in an IGF1R-dependent fashion." (PMID 40060910, 2025). "Here, using a surgical mouse model of secondary lymphedema, we demonstrated that targeting IGF1R signaling with linsitinib restricted both tissue swelling and pathological remodeling of LYVE-1+ lymphatics (i.e., initial and/or precollector lymphatics) during lymphedema development." (PMID 40060910, 2025).
Lynch syndrome (1 paper, 2015). An autosomal dominant hereditary neoplastic syndrome characterized by the development of colorectal carcinoma and a high risk of developing endometrial carcinoma, gastric carcinoma, ovarian carcinoma, renal pelvis carcinoma, and small intestinal carcinoma. "The IGF gene locus (coding for the ligand of IGF1R) has been reported as a genetic risk modifier for Lynch syndrome." (PMID 26517685, 2015).
male infertility (1 paper, 2025). The inability of the male to effect fertilization of an ovum after a specified period of unprotected intercourse. "Growth factor receptors, including EGFR, FGFR, and IGF1R, regulate essential testicular processes, sperm development and maturation, and their dysregulation has been linked to male infertility and testicular dysfunction." (PMID 40331996, 2025).
mastitis (1 paper, 2012). Inflammation of breast tissue during lactation or postpartum due to an obstructed duct or infection. "By means of positional cloning and functional analysis techniques, we here show that insulin-like growth factor 1 receptor (IGF1R) can possibly mediate susceptibility to mastitis through autophagy." (PMID 22973545, 2012). "As expected, cows derived from sires carrying 13G/13GFEZL and IGF1R with a longer C stretch have a greater incidence of clinical mastitis, suggesting that enhanced IGF1R is linked to slightly increased susceptibility to mastitis." (PMID 22973545, 2012). "In Bos taurus, a polymorphism in the 5UTR region of IGF1R was associated with mastitis incidence." (PMID 22973545, 2012). "Enhancing IGF1R inhibited autophagy in response to S. agalactiae invasion of bovine mammary epithelial cells [BMECs], suggesting that the susceptibility to mastitis might result from impaired autophagy." (PMID 22973545, 2012). "Next we continued to search genes responsible for susceptibility to mastitis on BTA21 and found that insulin-like growth factor 1 receptor (IGF1R) would be considered a positional candidate gene." (PMID 22973545, 2012). "Our results suggest that IGF1R could control innate immunity in mammals and serve as a potential tool for preventing mastitis." (PMID 22973545, 2012). "Indeed, cows carrying 13G/13GFEZL and IGF1R with a longer C stretch had a greater SCS among 478 cows from six half-sib Holstein sire families, indicating that they are susceptible to mastitis." (PMID 22973545, 2012). "Our five criteria might be arbitrary; however, we confirmed that correction for IGF1R and FEZL interaction reduced strongly the F-statistic and the effect of IGF1R on mastitis incidence was significant in independent samples." (PMID 22973545, 2012). "Based on the fulfillment of these five criteria, IGF1R appeared to be the most promising candidate gene, although we could not exclude the possibility that other genes on BTA21 might also influence resistance to mastitis." (PMID 22973545, 2012).
mesenchymal tumors (1 paper, 2023). "Another example of a promising oncoantigen includes the insulin-like growth-factor-1 receptor (IGF1R), which is involved in the progression of epithelial and mesenchymal tumors." (PMID 37629147, 2023).
metastatic cancers (1 paper, 2014). A carcinoma which has spread from the original site of growth to another anatomic site. "It seems unlikely that either of these events were drug related as there are no data to date showing that inhibition of IGF-1R perturbs coagulation and patients with metastatic cancers are known to be hypercoagulable." (PMID 24458261, 2014).
mucinous cystadenoma (1 paper, 2011). A benign or low malignant potential cystic epithelial neoplasm composed of cells which contain intracytoplasmic mucin. "The positivity rates of IGF-1R detection in serous and mucinous cystadenoma were 90% and 80%, respectively, which did not represent a significant difference (P > 0.05)." (PMID 22072919, 2011).
mucolipidosis II (1 paper, 2025). "These new findings raise the possibility that the dysfunction of the IGF1R signaling cascade may contribute to the pathophysiology of mucolipidosis II and III, considering that the failure to remove and renew cells has severe consequences on tissue organization and functions." (PMID 40332073, 2025).
Muscle spasm (1 paper, 2024). Sudden and involuntary contractions of one or more muscles. "Muscle spasms may be due to the interference of teprotumumab with the normal function of IGF-1R in skeletal muscle, which is important for muscle growth, repair, and contraction." (PMID 39185318, 2024).
myasthenia gravis (1 paper, 2025). Myasthenia gravis (MG) is a rare, clinically heterogeneous, autoimmune disorder of the neuromuscular junction characterized by fatigable weakness of voluntary muscles. "Comparison of clinical features of myasthenia gravis patients with IGF1R low and IGF1R high." (PMID 40152081, 2025).
oncocytoma (1 paper, 2019). "ErbB4, Insulin R, and IGF-1R were phosphorylated in the papillary RCC (RE0020), Mer (Axl family) was phosphorylated in the oncocytoma (RE0150), and HGFR, PDGFRα, and PDGFRβ were phosphorylated in the renal pelvic carcinoma (RE0210)." (PMID 31690270, 2019).
oropharyngeal carcinoma (1 paper, 2013). Carcinoma, predominantly squamous cell, arising from the epithelial cells of the oropharynx. "In addition, immunohistochemical staining of IGF-1R revealed that its abundance in the cytoplasm was remarkably lower in HPV-positive tumors than in HPV-negative tumors when compared with oropharyngeal carcinomas with a high level of IGF-1R expression." (PMID 23708675, 2013).
ovarian diseases (1 paper, 2023). "Insulin-like growth factor 1 receptor (IGFR) has already been established to participate in the regulation of folliculogenesis and ovarian diseases." (PMID 38037065, 2023).
ovarian granulosa tumour (1 paper, 2025). A granulosa-stromal cell tumor that arises from the ovary. "The mechanistic pathway involves GPR30 and the Insulin-like growth factor 1 receptor (IGF1R), a growth-promoting factor found in granulosa cells that responds to PFOS in human follicular fluid, thereby promoting the growth of ovarian granulosa tumours." (PMID 41228300, 2025).
Ovarian Hyperandrogenism (1 paper, 2021). Increased production of androgens by the ovaries. "Evidence suggests that ovarian hyperandrogenism is a result of insulin action on the ovaries, and because of that, it is mediated by IGF-1R." (PMID 33910166, 2021).
ovarian serous cystadenocarcinoma (1 paper, 2021). A malignant serous cystic epithelial neoplasm arising from the ovary. "More interestingly, the highest association scores between miR-150-5p/3p and IRS1 or IGF1R were found in 481 ovarian serous cystadenocarcinoma tissues through pan-cancer analysis by CancerMiner." (PMID 33723215, 2021).
Paralysis (1 paper, 2023). Paralysis of voluntary muscles means loss of contraction due to interruption of one or more motor pathways from the brain to the muscle fibers. "In this study, we aimed to investigate the effect of suppression of the IGF1R signaling pathway in BTX-induced muscle paralysis and thus analyzed the morphological changes in the NMJ, sprouting fibers, and the differentiation of SCs." (PMID 37717026, 2023). "The results showed that anti-IGF1R antibody administration inhibited the recovery from BTX-induced neurogenic paralysis, and the synaptic components at the neuromuscular junction (NMJ), mainly post-synaptic components, were significantly affected by the antibody." (PMID 37717026, 2023).
Pca (1 paper, 2015). "Simultaneously, androgen was found to up regulate the IGF-1R expression, which may also promote Pca development." (PMID 26186528, 2015).
peripheral nerve injury (1 paper, 2025). Injury to a peripheral nerve. "Previous studies reported that depletion of CD11c+ microglia or inhibition of IGF1/IGF1R signaling reinstated pain hypersensitivity in peripheral nerve injury models." (PMID 41276799, 2025).
peripheral vascular disease (1 paper, 2023). Any disorder affecting blood flow through the veins or arteries outside of the heart. "We found that APOE, IGF1R, HMGCR, APOA1, ENG, SERPINA3 and LCN2 were hub proteins in the network, which were also predicted to be associated with peripheral vascular disease." (PMID 37496672, 2023).
phyllodes tumor (1 paper, 2025). A benign, borderline, or malignant fibroepithelial neoplasm arising from the breast and rarely the prostate gland. "This comprehensive analysis elucidates the genomic landscape of phyllodes tumors, highlights molecular markers corresponding to histologic grade, broadens the range of tumors with frequent MED12 mutations, and identifies IGF1R and EGFR as potential therapeutic targets in malignant phyllodes tumors." (PMID 39996866, 2025).
pituitary adenomas (1 paper, 2021). "This could be of interest considering its role in regulating the IGF1R in several other tumors besides GH-secreting pituitary adenomas." (PMID 34484116, 2021).
pneumonia (1 paper, 2021). An acute, acute and chronic, or chronic inflammation focally or diffusely affecting the lung parenchyma, caused by an infection in one or both of the lungs (by bacteria, viruses, fungi, or mycoplasma.). "Some pneumonia viruses, such as syncytial virus, influenza, parainfluenza and calicivirus, can also use IGF-1R as a receptor." (PMID 34452353, 2021).